MIR578 (microRNA 578)
Synonyms: hsa-mir-578; MIRN578
Gene: MicroRNA gene on chromosome 4 (165,386,242 to 165,386,337, forward strand). Ensembl gene ENSG00000207559.
Gene Ontology:
Biological process: miRNA-mediated post-transcriptional gene silencing
Cellular component: RISC complex